PIN1 (peptidylprolyl cis/trans isomerase, NIMA-interacting 1)
Diseases named in the same sentence as PIN1 in open-access papers (continued):
Sharing a sentence is not in itself a finding about the gene and the disease.
papillary thyroid carcinoma (2 papers, 2011 to 2016). "The context and aim of this article was to investigate whether the expression level of Pin1 was in association with the clinical stage of papillary thyroid carcinomas." (PMID 27029791, 2016).
prostate adenocarcinoma (2 papers, 2013 to 2023). "In this analysis, we found Par14, like Pin1, to be overexpressed in prostate adenocarcinoma." (PMID 36583514, 2023).
renal cell carcinoma (2 papers, 2013 to 2020). "It has been reported that the expression levels of Pin1 are downregulated in renal cell carcinoma due to gene deletion and Pin1 restoration reduces tumor growth of human renal cell carcinoma cells." (PMID 32195254, 2020). "By contrast, previous studies have also shown that the downregulation of PIN1 expression is frequently observed in renal cell carcinoma (RCC) and gastric and testicular cancer." (PMID 24179535, 2013).
retinal degeneration (2 papers, 2016 to 2022). Degeneration of the retina. "Moreover, PIN1 knockout mice have demonstrated aberrant cell proliferation that resulted in various abnormalities such as retinal degeneration, neurological abnormality and testicular atrophy." (PMID 27258148, 2016).
Testicular atrophy (2 papers, 2016 to 2021). Wasting (atrophy) of the testicle (the male gonad) manifested by a decrease in size and potentially by a loss of fertility. "The genetic deletion of PIN1 may lead to testicular atrophy and a consequent reduction in fertility." (PMID 34113669, 2021).
thyroid cancer (2 papers, 2011 to 2016). "There have been few published articles about Pin1 expression in thyroid carcinoma, especially in PTC." (PMID 27029791, 2016). "Moreover, it has been suggested that Pin1 may promote cyclin D1 overexpression directly or through accumulation of beta-catenin in thyroid cancer cells." (PMID 21219594, 2011).
thyroid tumours (2 papers, 2011 to 2023). "Recently, in some reports - including the study on thyroid tumours - strong correlation between Pin1 and cyclin D1 immunoexpression and/or cyclin D1 mRNA and PIN1 expression via interaction with Wnt signalling pathway has been observed." (PMID 21219594, 2011). "There are rather scarce reports which are focused on evaluation of PIN1 mRNA expression in thyroid tumours." (PMID 21219594, 2011). "In immunohistochemical studies of thyroid tumours, as well as of other types of cancers (e.g., oral squamous carcinoma), high Pin1 expression promotes cyclin D1 overexpression, directly or through accumulation of beta-catenin." (PMID 21219594, 2011).
acute leukemia (1 paper, 2018). A clonal (malignant) hematopoietic disorder with an acute onset, affecting the bone marrow and the peripheral blood. "We found that PIN1 mRNA expression was significantly higher in bone marrow cells of acute leukemia (AL) patients compared to those of healthy controls (lane 2 versus lane 1)." (PMID 29848341, 2018). "Elevated expression of Pin1 was detected in acute leukemia patients in our study." (PMID 29848341, 2018).
acute lymphoblastic leukemia (1 paper, 2018). Leukemia with an acute onset, characterized by the presence of lymphoblasts in the bone marrow and the peripheral blood. "Besides, Pin1 activates the NOTCH3 signal by enhancing its cleavage and stabilizing its intracellular domain in T cell acute lymphoblastic leukemia (T-ALL) cell lines and mouse models." (PMID 30158600, 2018).
acute monocytic leukemia (1 paper, 2011). Acute monoblastic leukemia (AML-M5), is one of the most common subtypes of acute myeloid leukemia (AML) that is either comprised of more than 80% of monoblasts (AML-M5a) or 30-80% monoblasts with (pro)monocytic differentiation (AML-M5b). "Stimulation of a human acute monocytic leukemia cell line, THP-1 with PMA increased the PU.1 that bound Pin1-beads, but phosphatase treatment decreased the amount of PU.1." (PMID 21326608, 2011).
amyotrophic lateral sclerosis (1 paper, 2021). Amyotrophic lateral sclerosis (ALS) is a neurodegenerative disease characterized by progressive muscular paralysis reflecting degeneration of motor neurons in the primary motor cortex, corticospinal tracts, brainstem and spinal cord. "In addition, inhibition of Pin1 has been shown to reduce neurofilament (NFT)-H hyperphosphorylation and its pathological perikaryal accumulation in in vitro models of amyotrophic lateral sclerosis (ALS)." (PMID 33083964, 2021).
anemia (1 paper, 2019). A reduction in the number of red blood cells, the amount of hemoglobin, and/or the volume of packed red blood cells. "In the present study, we propose that the siRNA targeting PIN1 lncRNAs is a new therapeutic option for the management of CKD-associated anemia or other hypoxia-associated diseases." (PMID 31332228, 2019).
Anxiety (1 paper, 2023). Intense feelings of nervousness, tension, or panic often arise in response to interpersonal stresses. "Thus, phospho-mutations impede dynamic regulation of mGlu5 and its binding partners, with either Pin1 (GRM5AA/AA) or Homer2 (Homer2AA/AA) and produce a similar phenotype as that observed in GRM5R/R mice that cannot bind Homer, suggesting that regulation of mGlu5-Homer scaffolds promotes anxiety." (PMID 36973011, 2023).
arteriosclerosis (1 paper, 2013). A vascular disorder characterized by thickening and hardening of the walls of the arteries. "Neither the identity of Pin1 in hyperproliferative vascular disorders, such as arteriosclerosis and restenosis, nor the molecular mechanism of Pin1 function in these diseases was clear." (PMID 23750710, 2013).
autism (1 paper, 2025). Persistent deficits in social interaction and communication and interaction as well as a markedly restricted repertoire of activity and interest as well as repetitive patterns of behavior. "In conclusion, the authors were able to show that thymol enhanced autism-like behaviors in rats with valproic acid-induced autism spectrum disorder through the Pin1/p38 MAPK pathway by lowering inflammation and enhancing neurodevelopment." (PMID 40509336, 2025). "However, thymol treatment (30 mg/kg) resulted in a reduction of valproic acid-induced autism-like behaviors, and it also restored the dysregulated levels of Pin1, phosphorylated p38 MAPK, IL-1β, TNF-α, PSD95, and SYP." (PMID 40509336, 2025).
autism spectrum disorder (1 paper, 2025). A spectrum of developmental disorders that includes autism, and Asperger syndrome. "Through genetic suppression of Pin1, the authors also investigated the impact of Pin1/p38 MAPK on inflammation and synaptic development in a rat model of autism spectrum disorder caused by valproic acid." (PMID 40509336, 2025).
brain cancer (1 paper, 2018). A primary or metastatic malignant neoplasm affecting the brain. "The development of new and more selective inhibitors of PIN1 and other PPIases is therefore considered as an important step for anti-cancer approaches in several tumors, including brain cancers." (PMID 30314361, 2018).
brain injury (1 paper, 2024). Acute and chronic (see also brain INJURIES, CHRONIC) injuries to the brain, including the cerebral hemispheres, CEREBELLUM, and brain STEM. "Although further studies are needed to elucidate its protective mechanisms, our results demonstrate that PIN1 plays a neuroprotective role against ischemic brain injury, suggesting that it might be used as therapeutic protein for ischemic brain injury." (PMID 39457664, 2024).
brain tumor (1 paper, 2018). "Abnormal activation of PIN1 and other PPIases is frequently observed in brain tumors." (PMID 30314361, 2018). "Importantly, the relative levels of PIN1 expression are positively correlated with enhanced brain tumor progression." (PMID 30314361, 2018).
breast invasive ductal carcinoma (1 paper, 2023). "The objective of this study was to investigate the clinical significance and roles of tumor progression locus 2 (TPL2) and peptidyl-prolyl cis–trans isomerase 1 (Pin1) in the occurrence and development of breast invasive ductal carcinoma (IDC)." (PMID 37833434, 2023).
cardiac ischemia (1 paper, 2021). "A previous report found that at early reperfusion times, Pin1 protein levels exhibited a rapid decline after cardiac ischemia, which was with a pattern resembling that of AKT protein, indicating a relationship between Pin1 loss and AKT stability decreased." (PMID 34373763, 2021).
Cirrhosis (1 paper, 2019). A chronic disorder of the liver in which liver tissue becomes scarred and is partially replaced by regenerative nodules and fibrotic tissue resulting in loss of liver function. "A univariate Cox regression analysis was applied to identify important prognostic factors of recurrence-free survival, which tested parameters including age, gender, HBsAg status, cirrhosis, tumor size, TNM stage and Pin1/RhoA/RhoC co-expressions." (PMID 31324164, 2019).
cleidocranial dysplasia (1 paper, 2014). "RUNX2 is stabilized by a protein called PIN1, to the extent that Pin1 mutations give also rise to cleidocranial dysplasia-like phenotypes in mice." (PMID 24772099, 2014).
colitis (1 paper, 2021). Inflammation of the colon. "In addition, global Pin1 KO mice showed resistance to DSS-induced colitis development characterized by body weight loss, colon length reduction and epithelial tissue disruption." (PMID 34067858, 2021). "Moreover, Pin1 KO mice showed downregulation of both Il17 and Il23a expression in the colon, both of which have been implicated in the development of colitis." (PMID 34067858, 2021). "Besides the involvement of Th17 cells, multiple mechanisms underlying the contribution of hematopoietic Pin1 to the pathogenesis of colitis are possible." (PMID 34067858, 2021). "This is the first study demonstrating the pathological role of Pin1 in the development of DSS-induced colitis." (PMID 34067858, 2021). "In this study, first, we found that Pin1 protein was dramatically upregulated in the colons of dextran sodium sulfate (DSS)-induced colitis model mice, and therefore, investigated Pin1 involvement in the pathogenesis of IBD." (PMID 34067858, 2021). "Although further studies are necessary to fully elucidate the roles of Pin1 in colitis development, the development of new agents with high specificity for inhibiting Pin1 activity are eagerly awaited." (PMID 34067858, 2021). "Taken together, these findings show that orally-administered Pin1 inhibitor exerts a significant protective effect against DSS-induced colitis, raising the possibility of Pin1 inhibitors serving as novel therapeutic agents for treating IBDs." (PMID 34067858, 2021). "These datasets indicated that deletion of the pin1 gene ameliorates DSS-induced colitis development." (PMID 34067858, 2021). "We conclude that Pin1 plays a key role in the pathogenesis of DSS-induced colitis in mice." (PMID 34067858, 2021). "In other words, Pin1 plays an essential role in colitis development." (PMID 34067858, 2021). "Finally, oral administration of Pin1 inhibitor partially but significantly prevented DSS-induced colitis in mice, raising the possibility of Pin1 inhibitors serving as therapeutic agents for IBD." (PMID 34067858, 2021). "Finally, we investigated the effects of orally administered Pin1 inhibitor, Juglone, on the development of DSS-induced colitis in mice." (PMID 34067858, 2021). "Since Pin1 protein was markedly increased in the colonic tissues of DSS-treated mice, we speculated that Pin1 is involved in the development of colitis." (PMID 34067858, 2021).
COVID-19 (1 paper, 2021). A disease caused by infection with severe acute respiratory syndrome coronavirus 2. "This study is the first study to demonstrate the essential role of Pin1 in SARS-CoV-2 proliferation and the possibility of Pin1 inhibition as a promising therapy against COVID-19." (PMID 34535740, 2021). "Taken together, the results indicate that Pin1 inhibitors could serve as potential therapeutic agents for COVID-19." (PMID 34535740, 2021). "Accordingly, the use of Pin1 inhibitors might be an effective therapy against COVID-19." (PMID 34535740, 2021).
diabetic encephalopathy (1 paper, 2023). A brain disease that is characterized by functional impairment of cognition, cerebral signal conduction, neurotransmission and synaptic plasticity, and underlying structural pathology associated with diabetes. "We observed behavioral changes in mice and used molecular biology and histopathological to demonstrate that Pin1 may play an important role in the onset and development of diabetic encephalopathy by selectively upregulating Pin1 expression." (PMID 37990376, 2023). "Therefore, it is hypothesized that Pin1 may play an important role in protecting against diabetic encephalopathy." (PMID 37990376, 2023). "In addition, upregulating Pin1 expression could directly inhibit the excessive phosphorylation of Tau, ultimately reducing hippocampal neuronal apoptosis and alleviating cognitive dysfunction in mice with diabetic encephalopathy." (PMID 37990376, 2023).
diabetic nephropathy (1 paper, 2019). "Therefore, we can reasonably suggest that normalized Pin1 expression and AMPK activation contribute to the molecular mechanisms underlying SGLT2 inhibitor-induced suppression of diabetic nephropathy, possibly at least in part by reducing inflammation and fibrotic change." (PMID 31367234, 2019). "This is the first report, to our knowledge, to raise the possibility of Pin1 and AMPK involvement in the SGLT2 inhibitor-mediated protection against the development of diabetic kidney disease." (PMID 31367234, 2019). "Herein, we present the novel proposal that Pin1 and AMPK are involved in the protective action of SGLT2 inhibitors against diabetic nephropathy development." (PMID 31367234, 2019). "In the mesangial cells of diabetic mice, increased Pin1 might inhibit AMPK and decreased Pin1 by canagliflozin might activated AMPK, accounting for the contribution of canagliflozin to the amelioration of diabetic nephropathy." (PMID 31367234, 2019).
dysplastic nevi (1 paper, 2018). "The P value for the measured increase in cytoplasmic Pin1 expression in metastatic melanomas relative to dysplastic nevi was also very low (P = 0.016, χ2 test)." (PMID 30442923, 2018).
fetal growth restriction (1 paper, 2023). A fetus that does not grow beyond the 10th percentile of conventionally accepted weight for gestational age. "Importantly, cis-P-tau accumulation and protein aggregates in the placenta due to Pin1 inhibition were also accompanied with the PE-like pathological and clinical features, including fetal growth restriction, proteinuria, increased sFlt-1 and sEng production." (PMID 37669931, 2023).
germ cell tumor (1 paper, 2023). A benign or malignant, gonadal or extragonadal neoplasm that originates from germ cells. "Therefore, development of therapeutic strategies that specifically target Pin1 could provide a novel and effective treatment option for patients with TGCTs, particularly those with aggressive, nonseminomatous germ cell tumors." (PMID 38020885, 2023).
head and neck cancer (1 paper, 2013). A primary or metastatic malignant neoplasm affecting the head and neck. "Lu and coauthors also showed that the −842 G allele increased PIN1 expression compared to the −842 C allele in head and neck cancer cell lines, indicating that the variant −842 C allele reduced the promoter activity." (PMID 23874525, 2013).
hearing loss (1 paper, 2022). "In addition, in order to deeply investigate the effect of PIN1 on age-related hearing loss and possible mechanism, we further used juglone to inhibit the expression of PIN1 in HCs of young mice for in vivo experiments." (PMID 36340199, 2022). "In conclusion, our results showed that PIN1 might regulate autophagy activity to induce the senescent of HEI-OC1cells and HCs, which will provide a theoretical support for the prevention and treatment of age-related hearing loss." (PMID 36340199, 2022).
Heat Stroke (1 paper, 2019). A condition caused by the failure of body to dissipate heat in an excessively hot environment or during PHYSICAL EXERTION in a hot environment.
herpesvirus infection (1 paper, 2016). "Importantly, our studies on nuclear egress of the human cytomegalovirus (HCMV) suggested that the cellular peptidyl-prolyl cis/trans isomerase (PPIase) Pin1 is involved in lamina disassembly during herpesvirus infection." (PMID 27556400, 2016). "Intriguingly, this was observed in absence of herpesvirus infection proposing a broader importance of Pin1 for lamina constitution." (PMID 27556400, 2016).
hyperphosphatemia (1 paper, 2013). Abnormally high level of phosphate in the blood. "Four month-old Pin1 KO mice exhibit hyperphosphatemia that normalized in aged mice (18 month)." (PMID 23675491, 2013).
influenza (1 paper, 2016). An acute viral infection of the respiratory tract, occurring in isolated cases, in epidemics, or in pandemics; it is caused by serologically different strains of viruses (influenzaviruses) designated A, B, and C, has a 3-day incubation period, and usually lasts for 3 to 10 days. "Loss of Pin1 in HdhQ111 mice was able to counteract changes in “Wnt/β-catenin signaling”, “PCP pathway” and “Role of Wnt/GSK-3β signaling in the pathogenesis of influenza” as triggered by mHtt." (PMID 27199664, 2016). "“Wnt/β-catenin signaling”, “PCP pathway” and “Role of Wnt/GSK-3β signaling in the pathogenesis of influenza” are all changed in mHtt mice (repression) but in opposite direction when Pin1 is depleted (activation)." (PMID 27199664, 2016).
intrahepatic cholangiocarcinoma (1 paper, 2024). A carcinoma that arises from the intrahepatic bile duct epithelium in any site of the intrahepatic biliary tree. "Furthermore, c-Jun N-terminal kinase (JNK) has been found to phosphorylate Pin1 at residue Ser115, thereby inhibiting monoubiquitination at Lys117, which prevents proteasomal degradation and facilitates the progression of intrahepatic cholangiocarcinoma (ICC)." (PMID 39624096, 2024).
laryngeal carcinoma (1 paper, 2023). Carcinoma that arises from the laryngeal epithelium. "It makes sense to assume that the inhibition of laryngeal cancer cell growth and invasion by miR-150-5p is likely reversed by PIN1 overexpression." (PMID 37105032, 2023). "Therefore, the objective of this article was to investigate the regulatory effect of miR-150-5p on PIN1 and clarify the mechanism of miR-150-5p affecting the proliferation and invasion of laryngeal cancer cells." (PMID 37105032, 2023).
liver disease (1 paper, 2022). "Our study demonstrates a role of CK2 and PIN1 in reducing mitochondrial MATα1 content leading to mitochondrial dysfunction in alcohol-associated liver disease." (PMID 35091576, 2022). "Here, we show that mitochondrial MATα1 is selectively depleted in alcohol-associated liver disease through a mechanism that involves the isomerase PIN1 and the kinase CK2." (PMID 35091576, 2022).